FOXO1 (forkhead box O1)
Diseases named in the same sentence as FOXO1 in open-access papers (continued):
Sharing a sentence is not in itself a finding about the gene and the disease.
Insulin resistance (continued). "Whether FOXO1 plays similar roles like insulin resistance, in non-obese type 1 diabetic patients given that insulin deficiency is another characteristic feature of diabetes?" (PMID 26956801, 2016). "In addition, the expression of p-IRS2 and FOXO1 increased (p < 0.05, p < 0.0001, p < 0.001), and the expression of p-AKT decreased (p < 0.01) in the 15w-Z group, compared with the 15w-L group, confirming that insulin resistance appeared in the brain of 15-week-old ZDF rats." (PMID 34485269, 2021). "Independent of insulin resistance and obesity, sex steroids play vital roles in lipid and glucose metabolism by regulating the transcription of hepatic metabolic genes including carboxylase (ACC), transcription factor forkhead box protein O1 (Foxo1), SREBP-1, and FGF21." (PMID 34745420, 2021).
rhabdomyosarcoma (292 papers, 2001 to 2026). A rare aggressive malignant mesenchymal neoplasm arising from skeletal muscle. "Other frequently altered genes are RB1 and MYC (a well-known oncosuppressor and oncogene, respectively), NF1 (known for being often mutated in neural tumors), and PAXX (often fused with FOXO1 in alveolar rhabdomyosarcomas)." (PMID 40725011, 2025). "Our assay reported several diagnostic fusions, including PAX3 and PAX7 joining with FOXO1 in alveolar rhabdomyosarcoma and SS18-SSX fusion in synovial sarcomas." (PMID 40711866, 2025). "On univariate analysis in patients with localized disease, IRS (Intergroup Rhabdomyosarcoma Study) group, regional lymph node involvement (N0 vs.N1) and FOXO1 fusion status were associated with EFS and OS." (PMID 39781573, 2025). "PAX3::FOXO1 fusion should replace FOXO1 fusion as an adverse prognostic factor in risk stratification of patients with rhabdomyosarcoma." (PMID 39781573, 2025). "The current EpSSG overarching study for children and adults with frontline and relapsed rhabdomyosarcoma (FaR-RMS NCT04625907) includes FOXO1 fusion gene status in place of histology as a risk factor." (PMID 36980529, 2023). "The common fusions were identified in corresponding STS subtypes, e.g., FOXO1-associated fusions in rhabdomyosarcoma from the head or neck." (PMID 36928336, 2023). "Chromosomal translocations causing gene fusions between FKHR (Foxo1) and Pax3 or Pax7 are characteristic of alveolar rhabdomyosarcoma (ARMS), a pediatric soft tissue cancer derived from the muscle lineage." (PMID 33193700, 2020). "The importance of FOXO1 fusion status in risk stratification for treatment assignment in patients with rhabdomyosarcoma (RMS) has been controversial." (PMID 31456361, 2019). "The alveolar rhabdomyosarcoma is characterized by the chromosomal translocation that fuses the PAX3 or PAX7 genes with the gene encoding the transcription factor FOXO1/FKHR." (PMID 25341037, 2014). "Among the most studied examples, we can also mention the fusion of the DNA-binding domain of PAX3 or PAX7 transcription factors with the transactivation domain of FOXO1 (FKHR) in rhabdomyosarcoma (RMS) that is directly associated with gene expression dysregulation." (PMID 35682989, 2022). "A nice AP-1-associated enhancer regulation motif based on FOXF1 might also be a model for the family member FOXO1, which is exposed in our study and is associated with Rhabdomyosarcoma." (PMID 30563222, 2018). "Alveolar rhabdomyosarcoma (aRMS) is a pediatric soft tissue cancer commonly associated with a chromosomal translocation that leads to the expression of a Pax3:Foxo1 or Pax7:Foxo1 fusion protein, the developmental underpinnings of which may give clues to its therapeutic approaches." (PMID 28883017, 2017). "In the fusion oncoprotein PAX3-FOXO1, which drives alveolar rhabdomyosarcoma, a lysine-rich region of the FOXO1 IDR is subject to acetylation resulting in stabilization and enhanced transcriptional activity." (PMID 42284071, 2026). "PAX3::FOXO1 fusion gene is detected in 85% of alveolar rhabdomyosarcoma, while PAX7::FOXO1 fusion gene is seen in 10%." (PMID 40666501, 2025). "Alveolar rhabdomyosarcoma (ARMS) is an aggressive soft tissue sarcoma typically driven by the oncofusion protein PAX3::FOXO1 (P3F)." (PMID 41252925, 2025). "Abnormal signal patterns of FOXO1 amplification in alveolar rhabdomyosarcoma is a known common phenomenon." (PMID 40666501, 2025). "The prognostic relevance of PAX7::FOXO1‐positive and FN alveolar rhabdomyosarcoma (aRMS), along with the clinical factors described in this report, allows further refinement of risk assessment of patients with localized and metastatic (aRMS)." (PMID 39781573, 2025).
rhabdomyosarcoma (continued). "Our laboratory has previously demonstrated that alveolar rhabdomyosarcoma (ARMS) driven by the PAX3::FOXO1 (P3F) oncofusion protein can arise when P3F is expressed in endothelial progenitors in mice." (PMID 41252925, 2025). "FABP4 upregulation occurs via the forkhead box protein O1 (FOXO1), also known as FKHR (forkhead in rhabdomyosarcoma)." (PMID 41471323, 2025). "In the case of PAX3::FOXO1-driven rhabdomyosarcoma, inhibition of the RAS-ERK pathway leads to myogenic differentiation, similarly to normal muscle precursor cells." (PMID 38611033, 2024). "FOXO1 (a tumor suppressor), also referred to as FKHR (forkhead in rhabdomyosarcoma), belongs to the forkhead box O-class (FoxO) subfamily of transcription factors." (PMID 39273383, 2024). "This can directly determine how the fusion executes its oncogenic function: for example, PAX3::FOXO1 (fusion-positive rhabdomyosarcoma) binds DNA at sites determined by the PAX3 DNA-binding domains, whereas FOXO1 provides transactivating capacity." (PMID 39530749, 2024). "A similar phosphorylation event occurs at Ser203 in the PAX7 protein, another Group III PAX family member fused to FOXO1 in a subset of alveolar rhabdomyosarcoma." (PMID 38473380, 2024). "In vitro, AONs targeting PAX3 have been shown to inhibit PAX3::FOXO1 expression and trigger apoptosis in a fusion-positive rhabdomyosarcoma cell line." (PMID 38473380, 2024). "SAHA, a histone deacetylase inhibitor, and fenretinide, a vitamin A analog, have also been shown to reduce PAX3::FOXO1 protein levels in rhabdomyosarcoma cells." (PMID 38473380, 2024). "In the future, we plan to use these knockout zebrafish to understand the genetic cooperation between FGFR4 and PAX3::FOXO1, the predominant driver of fusion-positive rhabdomyosarcoma." (PMID 39576839, 2024). "The PAX3-FOXO1 fusion protein arises from a commonly observed genetic abnormality of alveolar rhabdomyosarcoma (aRMS) that results from the fusion of the DBD of PAX3 and the TAD of FOXO1." (PMID 37174744, 2023). "It has been reported that PAX3-Foxo1 can inhibit miR-221 and contribute to the pathogenesis of alveolar rhabdomyosarcoma, suggesting that Prx II regulates the expression of miR-221 through Foxo1." (PMID 37864270, 2023). "The tumor-specific chromosomal translocation product, PAX3::FOXO1, is an aberrant fusion protein that plays a key role for oncogenesis in the alveolar subtype of rhabdomyosarcoma (RMS)." (PMID 37732905, 2023). "Certain subtypes are strongly associated with genetic fusions, such as Ewing’s sarcoma (EWSR1::FLI1), alveolar rhabdomyosarcoma (PAX3/7::FOXO1), and synovial sarcoma (SS18::SSX1/2/4)." (PMID 36980578, 2023). "We detected EWSR1 fusions in three patients with Ewing sarcoma as well as a FOXO1 fusion in a patient with rhabdomyosarcoma, confirming the specificity of our assay." (PMID 36805676, 2023). "Translocations between 2q35 and 13q14 resulting in interaction of the FOXO1 enhancer B116Z with the Pax3 promoter have been observed in rhabdomyosarcoma cell lines." (PMID 37426677, 2023). "The diagnosis of alveolar rhabdomyosarcoma is confirmed by looking for the FOXO1 rearrangement for a single patient and the result was in favor of the histological diagnosis." (PMID 36164527, 2022). "Oncogenic FOXO1 gene fusions drive a subset of rhabdomyosarcoma (RMS) with poor survival; to date, these cancer drivers are therapeutically intractable." (PMID 36282590, 2022). "The presence of a FOXO1 fusion in a tumor is one of the most important prognostic factors in rhabdomyosarcoma." (PMID 36726902, 2022). "PAX3 was the 5′ fusion partner in 29 cases with 3′ partners being FOXO1 fusions identified in alveolar rhabdomyosarcoma cases, MAML3 and NCOA1 fusions in two different biphenotypic sinonasal sarcoma cases." (PMID 34745213, 2021). "PAX3/FOXO1 fusion accelerated PAX3/FOXO1-positive alveolar rhabdomyosarcoma aggregation by regulating PPP2R1A." (PMID 33817318, 2021).
rhabdomyosarcoma (continued). "In the PLAGL1:FOXO1 fusion observed here, the DNA binding domain of PLAGL1 is juxtaposed to the C-terminal TAD of FOXO1, which seems quite similar to PAX3:FOXO1 rearrangements as frequently observed in alveolar rhabdomyosarcoma." (PMID 34355256, 2021). "In a similar manner to the FOXO1 chromosomal translocation in alveolar rhabdomyosarcoma, FOXO3 (also known as FKHRL1) and FOXO4 (also known as AFX) are translocated to the MLL gene in mixed lineage leukaemia (MLL), an aggressive paediatric blood cancer." (PMID 32372224, 2020). "In humans, FOXOs were originally discovered in rhabdomyosarcomas and acute myeloid leukemias, in which three members (FOXO1, FOXO3 and FOXO4) were identified due to the chromosomal translocations that produce fusion proteins." (PMID 30646603, 2019). "As an example, rhabdomyosarcoma frequently contain recurrent gene fusions involving FOXO1 genes and PAX genes amid a changing landscape of genome mutations and structural variations." (PMID 31480361, 2019). "FOXO1, formerly called FKHR (forkhead in rhabdomyosarcoma), is a member of the forkhead box (FOX) family." (PMID 30487384, 2018). "Other proteomic studies have recently been carried out for soft tissue sarcomas with specific fusion genes such as EWS/FLI1 (for Ewing sarcomas) and PAX3/FOXO1 (for alveolar rhabdomyosarcoma)." (PMID 30680066, 2018). "Rhabdomyosarcomas (RMSs) are the most frequent soft tissue sarcoma in children and adolescents, defined by skeletal muscle differentiation and the status of FOXO1 fusions." (PMID 29898687, 2018). "The predictive value of FOXO1-related translocations in alveolar rhabdomyosarcoma has been investigated." (PMID 30487384, 2018). "The chromosomal translocation that leads to alveolar rhabdomyosarcoma development generates a novel TAD that is likely to favour ectopic PAX3:FOXO1 oncogene activation in non-PAX3 territories." (PMID 28615069, 2017). "Translocations involving PAX3 (or the closely related PAX7) and FOXO1 are only found in rhabdomyosarcomas." (PMID 28615069, 2017). "In a specific tumor type, dysregulation of Hippo signaling arises from a translocation fusion oncogene involving another FOX family member, FOXO1 in rhabdomyosarcoma." (PMID 27074562, 2016). "FOXO1 also plays a role in metastasis and invasion in T lymphocyte cancer, rhabdomyosarcoma, ovarian cancer, breast cancer, and prostate cancer." (PMID 27486383, 2016). "FOXO1 (also known as forkhead in rhabdomyosarcoma, or FKHR) is a member of the forkhead box O (FOXO) family." (PMID 27244896, 2016). "The FOXO1 gene was particularly interesting since it is fused to either the PAX3 gene or the PAX7 gene in alveolar rhabdomyosarcoma." (PMID 25341037, 2014). "In our studies, we sought to refine experimentally the range of possibilities for the cell of origin of Pax3:Foxo1+ rhabdomyosarcoma." (PMID 25030697, 2014). "Furthermore, ALK is expressed on the cell surface of rhabdomyosarcomas harboring a PAX3 or PAX7::FOXO1 fusion (fusion-positive rhabdomyosarcoma), the most common soft tissue sarcoma of childhood and adolescence." (PMID 40813394, 2025). "Therefore, rhabdomyosarcoma occurs when PAX3 fuses with FOXO1, altering the structure of chromosome 2." (PMID 38540335, 2024). "Interestingly, it has been shown that in rhabdomyosarcomas which express the PAX3::FOXO1 fusion protein, Ser205 remains phosphorylated even as myogenic differentiation is triggered." (PMID 38473380, 2024). "In addition, a PAX3-FOXO1 fusion protein hampered the differentiation of rhabdomyosarcoma cells, supporting a potential anti-tumorigenic connection among FOXO1, type I myofiber phenotype, and cancer." (PMID 38928185, 2024). "CDKN2A/B), amplifications (e.g. JUN in liposarcoma), fusion partners (e.g. PAX3/7::FOXO1 in rhabdomyosarcoma), breakpoint positions in fusions (e.g. NAB2::STAT6 in SFT) and the extent of segmental (i.e. sub-chromosomal arm) copy number changes (e.g. synovial sarcoma)." (PMID 38997407, 2024).
rhabdomyosarcoma (continued). "Alveolar rhabdomyosarcoma (ARMS)—an invasive subtype of rhabdomyosarcoma—is characterised by fusion of Pax3 or Pax7 genes on chromosome 1 and 2, respectively, with the FOXO1 gene; which encodes Pax3-FOXO1 and Pax7-FOXO1 fusion proteins." (PMID 38995522, 2024). "However, these miRNAs are incapable of reducing the expression of the oncogenic fusion protein PAX3::FOXO1 in alveolar rhabdomyosarcoma, as the fusion protein lacks the 3′UTR that would normally be the target for these miRNAs." (PMID 38473380, 2024). "Additionally, FOXO1 fusion status was predicted accurately for 97.4% of rhabdomyosarcomas and MYCN amplification was predicted with 88% accuracy in neuroblastoma." (PMID 39169157, 2024). "Finally, we developed a hybridization-based capture panel to target EWSR1 and FOXO1 fusions from patients with Ewing sarcoma or alveolar rhabdomyosarcoma (ARMS), respectively." (PMID 36805676, 2023). "Single-cell PAX3:FOXO1 expression in rhabdomyosarcoma is variable." (PMID 34187933, 2021). "The mammalian Forkhead box O (FoxO) family includes four members expressed nearly in all tissues: FoxO1 (forkhead in rhabdomyosarcoma, FKHR), FoxO3 (forkhead in rhabdomyosarcoma like protein 1, FKHRL1), FoxO4 (acute leukemia fusion gene located in chromosome X, AFX), and FoxO6." (PMID 32244542, 2020). "Fusions of FOXO1 have been found in pediatric alveolar rhabdomyosarcoma and childhood B-ALL." (PMID 33262946, 2020). "Alveolar rhabdomyosarcoma is a high grade neoplasm that has the worst prognosis amongst other subtypes of RMSs (despite combined surgical and chemo/radiotherapy), especially in fusion-positive cases when FOXO-1 gene is involved." (PMID 27756397, 2016). "The Akt/PKB pathway promotes cell survival by regulating a number of transcription factors, including the forkhead transcription factor superfamily, such as Forkhead box protein O1 (FoxO1, also known as fork head in rhabdomyosarcomas [FKHR]), FoxO3a (FKHRL1), FoxO4 (AFX) and FoxO6." (PMID 23029264, 2012). "The FOXO (Forkhead box, class O) is a subfamily of forkhead transcription factor and consists of FOXO1A (FKHR: Forkhead in rhabdomyosarcoma, also known as FOXO1), FOXO3A (FKHR-like 1), MLLT7 (AFX: acute-lymphocytic-leukaemia-1 fused gene from chromosome X, also known as FOXO4) and FOXO6." (PMID 21696576, 2011). "The alveolar rhabdomyosarcoma histopathological and genetic variant exhibits frequent metastasis, worse prognosis, and the acquisition of somatic balanced chromosomal translocations with novel fusion genes (paired-box transcription factor 3 (PAX3) or 7 (PAX7) and forkhead box protein O1 (FOXO1))." (PMID 37510264, 2023). "Therefore, based on these functional backgrounds, silencing of co-activator SS18/SSX picked up small amounts of regulated proteins compared to Ewing sarcoma and alveolar rhabdomyosarcoma having either EWS/FLI1 or PAX3/FOXO1 which act as transcriptional factors." (PMID 30680066, 2018). "The rhabdomyosarcomas were FOXO1 fusion-negative, hinting at a higher number of mutations." (PMID 28424409, 2017). "In this study, we hypothesized that screening a small-molecule library might identify already existing drugs that are able to modulate the transcriptional activity of PAX3/FOXO1, the fusion protein specifically found in the pediatric tumor alveolar rhabdomyosarcoma (aRMS)." (PMID 23372815, 2013). "In fusion-positive rhabdomyosarcoma, the DNA-binding capabilities of PAX3 or PAX7 are fused with the transcriptional activating domain of FOXO1." (PMID 40983796, 2025).